RNU6-241P (RNA, U6 small nuclear 241, pseudogene)
Gene: Small nuclear RNA gene on chromosome 7 (45,789,585 to 45,789,688, forward strand). Ensembl gene ENSG00000212450.
Homologues: Orthologues: chimpanzee U6 (100% identical), macaque U6 (92% identical), pig U6 (83% identical), pig U6 (79% identical), dog U6 (78% identical). Paralogues in human: RNU6-1319P (100% identical), RNU6-747P (100% identical), RNU6-1076P (99% identical), RNU6-1100P (99% identical), RNU6-1118P (99% identical), RNU6-1217P (99% identical), RNU6-355P (99% identical), RNU6-447P (99% identical), RNU6-785P (99% identical), RNU6-791P (99% identical), RNU6-860P (99% identical), U6 (99% identical), and 1287 more.